ENSG00000272897 (novel protein)
Gene: Protein-coding gene on chromosome 20 (35,632,340 to 35,674,544, reverse strand). Ensembl gene ENSG00000272897.
Genetic constraint (gnomAD): Missense variants: 102 observed, 139.32 expected, observed/expected ratio (o/e) 0.73, 90% interval 0.62 to 0.86. Synonymous variants: 44 observed, 54.85 expected, observed/expected ratio (o/e) 0.8, 90% interval 0.63 to 1.03.